MTOR (mechanistic target of rapamycin kinase)
Diseases named in the same sentence as MTOR in open-access papers (continued):
Sharing a sentence is not in itself a finding about the gene and the disease.
tumor (continued). "The hamartin and tuberin heterodimer has been shown to function as a tumor suppressor by inactivating mTOR through suppression of the small GTPase Rheb (Ras-homolog enriched in brain)." (PMID 30842342, 2019). "The rare PNET have also been found to have mTOR hyperactivity, with one study demonstrating that 85% of primary tumours had altered protein levels of the tumour suppressors TSC2 and PTEN." (PMID 35582282, 2019). "On the other hand, a remarkable early finding showed that in a set of tumor types the overexpression of GOLPH3 enhances the activity of the mTOR-signaling pathway." (PMID 30779783, 2019). "Such genes include DNA repair genes (BRCA1, PCNA), a regulator of oxygen homeostasis (HIF1-alpha), anti-apoptotic genes, tumor suppressors, genes of the Akt/mTOR signaling pathway and vascular endothelial growth factor A (VEGFA)." (PMID 31205871, 2019). "mTOR signalling integrates both intracellular and extracellular signals and works as a central pathway in tumour progression and malignancy." (PMID 31747912, 2019). "In colorectal cancer, the combined treatment of Trametinib and Everolimus, a MAPK/ERK pathway inhibitor and mTOR inhibitor, respectively, results in significant inhibition of tumor growth." (PMID 31366089, 2019). "To test the mTOR pathway we treated A52 tumors with the mTOR inhibitor Rapamycin and it effectively restricted tumour growth (p = 0.0001)." (PMID 30794695, 2019). "Subsequent combinatorial inhibition of mTOR and Src with Rapamycin and Dasatinib dramatically reduced A52 tumor growth and importantly, we observed activity of the mTOR and Src pathways in human HCC." (PMID 30794695, 2019). "While finely tuned mTOR signaling is essential for normal CNS development, GSCs take advantage of an improper mTOR activity to fuel tumor growth and infiltration." (PMID 31387280, 2019). "Mechanistically, PIPKIγ facilitated PI3K-Akt-mTOR signaling pathway activation to increase STAT3 phosphorylation levels, thus triggering CCL2 transcription to enhance tumor-associated macrophage recruitment." (PMID 31781676, 2019). "Lactate in the TME is imported by tumor cells and upregulates mTOR signaling via glutamine metabolism during treatment with vascular endothelial growth factor (VEGF) inhibitors." (PMID 30927928, 2019). "The activation of autophagic signaling pathway is mediated by downregulation of AKT/mTOR/p70S6K being a crucial target of Salmonella in tumor cells." (PMID 31052558, 2019). "It is well known that the mTOR pathway regulates tumor growth and metastasis by mediating tumor metabolic homeostasis." (PMID 31637133, 2019). "The PI3K/AKT/mTOR signaling pathway was involved in extensive intracellular phosphorylation, and was found to be widely activated in a variety of tumor types." (PMID 30636930, 2019). "In summary, we demonstrate that MACC1 regulates PDL1 expression and tumor immunity through the c‐Met/AKT/mTOR pathway in GC cells." (PMID 31557409, 2019). "We strongly believe that mTOR inhibitors should be preferably indicated in patients with proven histological mTOR pathway upregulation within the tumour but a randomized trial focused in this subpopulation is needed to reinforce this rationale." (PMID 30650598, 2019). "We show here that β-elemene inhibits the phosphorylation of IR and the downstream factors, including PI3K, PRAS40, mTOR and S6 ribosomal protein specifically in tumor cells." (PMID 30422809, 2019).
tumor (continued). "The mechanistic pathway can be simplified by inactivating AMP-activated protein Kinase (AMPK), activating the mammalian target of rapamycin (mTOR) signaling pathway, and consequently increasing tumor development." (PMID 30863490, 2019). "Tuberosclerosis gene TSC1 (9q34) and TSC2 (16p13.3) are regulated by neurofibromin through mTOR activation, linking the three proteins in terms of their potential roles in tumour progression." (PMID 31443481, 2019). "The expressions of Ras, Erk1/2, Myc, mTOR and NF-κB p65 protein in tumor tissues of 2 groups were detected by Western blot, and these were decreased by treated with Adv-mfn2 comparing with the Adv-control group." (PMID 31384172, 2019). "Like AMPK, LKB1 appears to serve as a context-dependent tumor promoter, and activation of this signaling pathway can be decoupled from regulation of mTOR signaling." (PMID 31798532, 2019). "EpCAM in PCa is associated with tumor progression and metastasis and therapeutic resistance via the PI3K/Akt/mTOR signaling pathway." (PMID 31324239, 2019). "Together, we conclude that kindlin-2 promotes angiogenesis and tumour progression via mTOR signalling." (PMID 31427543, 2019). "The activation of Akt/mTOR signaling decreased sensitivity to chemotherapy, as far as the tolerability is concerned, so we need to inhibit this pathway to increase anti-tumor drugs effect." (PMID 31871431, 2019). "As reported, the ATP competitive mTOR inhibitor MLN0128 showed better efficacy in reducing tumor size and invasion in cell lines and Pca mouse models." (PMID 30754640, 2019). "This drug must induce longer-lasting anti-tumor effects by profoundly blocking mTOR signaling and simultaneously preventing undesired feedback mechanisms." (PMID 31010254, 2019). "UL38’s metabolic reprogramming role is dependent on its interaction with TSC2, a tumor suppressor that inhibits mTOR signaling." (PMID 30677091, 2019). "Rapamycin and its derivatives are mTOR inhibitors reported to serve as autophagy inducers with anti-tumor activity in a phase II study on 25 advanced HCC patients." (PMID 30849993, 2019). "PI3K/Akt/mTOR signaling negatively regulates autophagy while the tumor suppressor PTEN activates autophagy via suppression of PI3K/Akt/mTOR signaling." (PMID 31358051, 2019). "mTOR activity is also regulated by a number of oncoproteins and tumor suppressors, including AMP-activated protein kinase (AMPK), protein kinase B (AKT) and more recently, the non receptor tyrosine kinase (non-RTK) Src." (PMID 30794695, 2019). "NIS, Beclin1, p-AMPK and p-mTOR were detected by immunohistochemical staining and Western blot in transplanted tumor samples." (PMID 31331356, 2019). "Second generation mTOR inhibitors have shown stronger preclinical anti-tumor activity than allosteric mTOR inhibitors." (PMID 31167506, 2019). "These signaling pathways, including the mTOR, NF-κB, AKT, and STAT3 pathways, are generally associated with tumor cell proliferation and survival." (PMID 30927928, 2019). "‘MAPK/mTOR’ and ‘Null’ signature tumours co-existed in animals #3 and 6, indicating inter-tumour signature heterogeneity." (PMID 31772293, 2019). "The persistent activation of PI3K/Akt/mTOR pathway is known to be involved in tumor development and resistance to anticancer therapies." (PMID 31683659, 2019). "What’s more, combination therapy with ALM significantly enhanced mTOR inhibitors’ effect on tumor suppression." (PMID 31083403, 2019). "We demonstrated that a PDC model derived from an acquired-resistant tumour was successfully suppressed by PI3K/mTOR inhibitors such as AZD-8055 or BEZ-235." (PMID 31653970, 2019). "Although mounting evidence suggests that mTOR regulates nucleotide metabolism in cultured cells and tumor models, the relevance of this relationship in normal animal development has not been well defined." (PMID 30857853, 2019).
tumor (continued). "The PI3K/Akt/mTOR signaling pathways have been identified as contributing to tumor progression, and which are important regulators of several functions." (PMID 30678221, 2019). "In other words, the mTOR activity within the tumour would mirror the actual tumour proliferation status while the mTOR expression in the tumour edge would be confounded by other coexisting phenomena such as peritumour innate inflammation response." (PMID 30650598, 2019). "The patient with 5% p-mTOR staining was a 26-year-old woman with stage 3c disease, 5 cm tumor size, widespread tumor implants, 19 mitoses in 10 high-power field (HPF), and high-grade atypia." (PMID 30592193, 2019). "When STAM mice treated with INK-128 (an mTOR inhibitor) were exposed to hypoxia, they developed fewer tumours and smaller tumour sizes." (PMID 31796646, 2019). "mTOR not only has a major role in tumour progression but also plays a role as the central regulator of autophagy." (PMID 30970654, 2019). "Knockdown of ATF6α prolonged the survival of nude mice bearing dormant tumor cells through the ATF6α-Rheb-mammalian target of rapamycin (mTOR) pathway in a p38-dependent manner." (PMID 30857233, 2019). "Treatment with rapalogs has been shown to improve clinical outcomes and cause tumor regression in TSC patients with astrocytomas or sporadic LAM, again suggesting a dependence on mTOR signaling for tumor growth." (PMID 30764584, 2019). "Collectively, our findings confirmed that Notch1 promotes GICs invasion self-renewal and tumor growth through the AKT/mTOR pathway mediated by CXCL12/CXCR4 axis and thus provide evidence of a promising target for GBM management." (PMID 31382985, 2019). "Notch and PI3K/Akt/mTOR also contribute to the development of OS, and the inhibitors targeting PI3K, Akt, mTOR or Notch signaling demonstrates robust suppression on the proliferation of OS cells in vitro and the OS tumor growth in vivo." (PMID 31788020, 2019). "Under the stimulation of TC-1 tumor cells, the phosphorylation of mTOR and p38 were activated and expression of apoptotic molecules, Bad and Bak were up-regulated in non-mTORi-treated BMM-derived DCs (lane 2)." (PMID 31052575, 2019). "Constitutive activation of PI3K/Akt/mTOR signaling cascades has been reported to play an essential role in the survival and metastasis of tumor cells." (PMID 30609689, 2019). "We noted that CTC in combination with BEZ-235 can effectively down modulate the phosphorylation of AKT/mTOR proteins and induce substantial apoptosis in tumor cells." (PMID 30813295, 2019). "Luteolin is a type of flavonoid that inhibits proliferation involving MAPK and mTOR signalling pathways in various tumour cell lines." (PMID 30609679, 2019). "The PI3K/Akt pathway is characterized as a critical regulator of tumor cell metabolism, growth, proliferation, and survival, and the downstream molecule of mTOR has an array of biological functions that promote hypoxic adaption and protein translation." (PMID 31245283, 2019). "Overall, our results conclusively demonstrate that CTC can function as a potential inhibitor of tumor cell survival and proliferation by negatively regulating Akt/mTOR activation." (PMID 30813295, 2019). "The mTOR pathway is activated in HCCs and manipulation of mTOR inhibitors shown to effectively exert anti-tumor effects in HCC." (PMID 30849993, 2019). "It is noteworthy that PD-L1 derived from tumor cells can facilitate tumor glycolysis through AKT/mTOR signaling." (PMID 31379886, 2019). "Subsequently, we use an immunohistochemical assay to determine the protein expression of p‐AKT3 and p‐mTOR from nude mice tumor tissues." (PMID 31207155, 2019). "In our ATC xenograft model, JPH203 administration with a dose of 12.5 mg/day also suppressed the tumor growth through blocking downstream mTOR signaling pathway." (PMID 31601917, 2019).
tumor (continued). "One of the paramount signaling pathway, Notch/AKT/mTOR in tumor aggressiveness, has reported to be downregulated by quercetin plus shHSP27, leading to significant apoptosis in U937 leukemia cells." (PMID 31064104, 2019). "The mTOR pathway modulates the interactions between the stroma and the tumor, thereby affecting both tumor immunity and angiogenesis." (PMID 31766386, 2019). "While mTOR inhibitors, such as rapamycin or everolimus, are clearly effective against different tumor types in TSC, their efficacy against neurological symptoms of TSC is more limited." (PMID 31838997, 2019). "Since glucose is the main fuel source of CRC cells, an activated AKT/mTOR pathway promotes tumor cell proliferation." (PMID 30987065, 2019). "It is caused by mutations in either the TSC1 or TSC2 gene, which result in upregulation of the mammalian target of rapamycin (mTOR) pathway and subsequent tumor growth in various organs such as the brain, heart, skin, eyes, kidney, lung, and liver." (PMID 31039793, 2019). "Phospho-mTOR, which is activated by Akt, can promote proliferation and indirectly protect tumor growth." (PMID 31015849, 2019). "Albeit the expected positive effects of combined vincristine and rapamycin on CTVT regression, the tumor feedback mechanisms against PI3K/mTOR inhibitors should also be regarded as possible drug-resistant complication." (PMID 31193204, 2019). "Intrinsic PD-L1 signaling promotes tumor cell proliferation and growth in melanoma and ovarian cancer cells by regulating autophagy and the mTOR pathway, and protects tumor cells from interferon (IFN)-mediated cytotoxicity." (PMID 31718692, 2019). "MLN0128 is a second-generation mTOR ATP site inhibitor and can reduce the tumor burden effectively in CD44 expressing HCC, which is insensitive to sorafenib." (PMID 31277283, 2019). "The inhibition of both pathways leads to an early decrease in tumour volume in some models but this appears to convert to stasis if only mTOR inhibition is sustained." (PMID 31822716, 2019). "In one such example, a possible feedback loop between Akt and ERK/MAPK signalling by mTOR inhibition was found to act as a survival mechanism in tumour cells." (PMID 31308358, 2019). "In future randomized trials, the mTOR pathway expression should be assessed within the tumour in order to avoid the potential confounding effect of peritumour inflammation." (PMID 30650598, 2019). "For instance, patients treated with the mTOR inhibitors temsirolimus and sirolimus showed a measurable concentration of temsirolimus and sirolimus in tumor tissue." (PMID 31013819, 2019). "In other hematological malignancies, it was shown that tumor cells activate the AKT/mTOR pathway in MSC and elicit VEGF and HIF-1 production." (PMID 31547627, 2019). "(F) The expression of p-mTOR, p-S6 and 8-OHdG was examined by IHC analysis of xenograft tumour tissues from Balb/c nude mice treated with verteporfin and DOX (scale bar: 50 μm/25 μm)." (PMID 31337986, 2019). "To date, only few data exists on the impact of tumor heterogeneity on the potential prognostic role of mTOR parameters as biomarkers in PC." (PMID 31885728, 2019). "HRAS belongs to the Ras oncogene family, and HRAS mutants are known to aberrantly activate mTOR signalling in HNSCC tumours." (PMID 30970654, 2019). "In the present study, we initially demonstrated that the expression of important regulators of the mTOR pathways differs in the tumor center, the tumor invasion front, the tumor-adjacent benign tissue, and the tumor-distant benign tissue." (PMID 31885728, 2019). "The abnormal activation of mTOR promotes proliferation and inhibits the apoptosis of tumor cells via activating Akt." (PMID 31724536, 2019). "In a cancer model mimicking the tumor microenvironment, IL-33 directly affected the survival of tumor cells by activation of mTOR." (PMID 31396219, 2019).
tumor (continued). "We similarly performed spatial analysis on TMA sections representing 25 clinical PAC samples, and confirmed that both ‘MAPK/mTOR’ signature (PAC_4,8,18) and ‘Null’ signature tumours were detected in clinical PACs." (PMID 31772293, 2019). "In vitro studies with dual inhibition of PI3K and mTOR have established a strong anti-tumor activity in LMS, which was seen to be significantly higher than either agent alone." (PMID 31416195, 2019). "In order to investigate the effects of tumour development on muscle protein signalling, we analysed several key proteins of mTOR pathway obtained from rats at 7, 14 and 21 days following tumour development, analysing the proteogenesis cell signalling via." (PMID 30975087, 2019). "Rapamycin (mTOR pathway inhibitor) can diminish the invasion of tumor cells by down‐regulating the expression of pS6, which demonstrated that the inhibitors of mTOR pathway have a broad application in the remedy of BC." (PMID 30907072, 2019). "AKT/mTOR and Wnt3a/β-catenin, key pathways in regulating tumor proliferation and metastasis, were found to be inactivated by the down-regulation of PBF in ESCA cells." (PMID 31637306, 2019). "As previously stated, hypoxia influences metabolic pathway related to the control of cell metabolism including PI3K/AKT/mTOR favoring tumor proliferation and resistance." (PMID 31214505, 2019). "In particular, the survival of tumor patients is affected by upregulated PI3K/AKT/mTOR cascade activity." (PMID 31929797, 2019). "Subsequently, Spa-RQ was applied to measure the co-activation of MAPK, AKT, and their mutual effector mTOR pathway in individual tumours." (PMID 31772293, 2019). "In animal and cell culture studies dysregulation of PI3K, Akt, and mTOR was led to tumor formation, while knocking out of PI3K, Akt, or mTOR, blocked this oncogenic transformation, inhibited tumor growth and blocked its invasiveness." (PMID 30881282, 2019). "Meanwhile, DAP2IP, a tumor suppressor, plays an important role in drug resistant by regulating mTOR." (PMID 30945310, 2019). "Metformin inhibits mTOR phosphorylation by activating AMPK in the AMPK/mTOR signaling pathway, thereby leading to the arrest of tumor cell cycle and the inhibition of cell growth and proliferation, which finally results in cell apoptosis." (PMID 31467666, 2019). "While mTOR inhibition did enhance cell survival under hypoxia in these tumor cells, these effects were overall less pronounced." (PMID 31510109, 2019). "Although mTOR inhibitors can slow tumor growth, they have the potential to promote metastasis by activating TGF-β signaling." (PMID 31228948, 2019). "A striking epithelioid SEGA-like morphology and strong mTOR activation were diffusely noted in our 3rd patient’s tumor." (PMID 31258848, 2019). "This metabolic switch, dependent on the active axis PI3K-AKT, a part of the receptor tyrosine kinase/PI3K/AKT/mammalian target of rapamycin (RTK/PI3K/AKT/mTOR) signaling pathway, accelerates tumor proliferation and contributes to its aggressiveness." (PMID 30857125, 2019). "It was reported that TNBC was subclassified into at least six tumor molecular subtypes including a mesenchymal-like subset that was highly sensitive to PI3K/mTOR inhibitors in vitro and in vivo." (PMID 30713576, 2019). "COR induces apoptosis of tumor cells through mitochondria (caspases) and the mTOR and autophagy pathways, as well as by inhibiting ER stress-induced injury." (PMID 31207985, 2019). "Suppression of the mTOR pathway has been reported to inhibit the growth of GC cells in vitro and delay tumor progression in animal models." (PMID 30866995, 2019). "The tumor growth inhibition and decrease in size by JPH203 via inhibition of mTOR signaling and G0/G1 cell cycle associated proteins were further confirmed in xenograft models." (PMID 31601917, 2019). "This mTOR inhibitor generated contrasting results when employed on thyroid tumors as efficacy was mostly dependent on tumor type and stage." (PMID 31269742, 2019).